CCL19 (C-C motif chemokine ligand 19)
Diseases named in the same sentence as CCL19 in open-access papers (continued):
Sharing a sentence is not in itself a finding about the gene and the disease.
atopic dermatitis (5 papers, 2014 to 2024). "CCL19-expressing fibroblasts have been identified in atopic dermatitis and localize to leukocyte-rich areas of the skin." (PMID 39190494, 2024). "A number of chemokines [CCL2, CCL3, CLL4, CCL8, CCL13, CCL19, chemokine (C-X-C motif) ligand (CXCL) 1, CXCL6, CXCL16] were upregulated in sensitized dogs after allergen challenge, similar to what is observed in human atopic dermatitis." (PMID 25098772, 2014).
Autoimmunity (5 papers, 2011 to 2022). The occurrence of an immune reaction against the organism's own cells or tissues. "Notably, besides migration, CCL19/CCl21 chemokines have been correlated with autoimmunity and immune suppression indicating an important additional role balacing immunity and tolerance." (PMID 21483789, 2011).
breast tumor (5 papers, 2013 to 2024). "Upregulation of Ccl19, Ccl20 and chemokine (C-X-C motif) receptor (Cxcr) 2 has also been associated with breast tumor growth and invasion, Cxcr2 particularly with angiogenic processes." (PMID 24156623, 2013). "Therefore, Ifng activates the Ccl19/Ccl21/Ccr7 axis between breast tumors and SRC-3 KO Tregs to signal the recruitment of SRC-3 KO Tregs into breast tumors." (PMID 37253006, 2023). "As CCL19 can be secreted by APC subsets, it would be interesting to unravel the nature of putative CCL19+ BM APC that could potentially present breast tumor antigens to Treg." (PMID 28224210, 2017).
colitis (5 papers, 2013 to 2024). Inflammation of the colon. "On the other hand, colitis rats receiving feed with high-molar-mass oat beta-glucan (CβGh+) resulted in higher expression of only four genes (Ccl19, Ccr4, Ccr8, Cxcl9)." (PMID 35163326, 2022). "CD69-deficient mice showed increased transcript levels of some chemokine genes, such as CCL-1, CXCL-10 and CCL-19 in steady-state conditions and after colitis induction." (PMID 23776480, 2013). "In DSS colitis CD69−/− CD4 T cell accumulation in colonic lamina propria (cLP) was associated with increased expression of CCL-1, CXCL-10 and CCL-19 genes." (PMID 23776480, 2013). "Similarly, colitis rats receiving feed with low-molar-mass oat beta-glucan (βGl+) upregulated the expression of only four genes (Ccl19, Cxcl10, Cx3cr1, Cxcr5) in this stage of colitis." (PMID 35163326, 2022). "Furthermore, treatment of DSS-administrated CD69−/− mice with the mixture of CCL-1, CXCL-10 and CCL-19 neutralizing Abs significantly decreased the histopathological signs of colitis." (PMID 23776480, 2013). "In DSS colitis model this was at least partially dependent on the increased expression levels of the chemokines CCL-1, CXCL-10 and CCL-19 in the colon of CD69-deficient animals, as neutralization of these three chemokines significantly improved the histopathological picture in colon." (PMID 23776480, 2013). "The treatment of DSS-induced colitis in CD69−/− mice with the mixture of Abs that neutralize CCL-1, CXCL-10 and CCL-19 did not affect the accelerated body weight loss, but it reduced significantly the histopathological severity of the disease." (PMID 23776480, 2013). "Severity of the colitis could be ameliorated in DSS-administrated CD69-deficeint mice with the neutralization of CCL-1, CXCL-10 and CCL-19." (PMID 23776480, 2013).
diabetic nephropathy (5 papers, 2021 to 2025). "MicroRNA-325-3p is an anti-inflammatory agent that suppresses renal inflammation and fibrosis in diabetic nephropathy by directly downregulating CCL19." (PMID 35222545, 2022). "In summary, this study provides novel insights into the pathogenesis of diabetic nephropathy and identifies CCL19 as a potential critical gene of DN." (PMID 35222545, 2022). "CCL19 could be targeted and inhibited by miR-325-3p to attenuate renal inflammation in diabetic nephropathy mice." (PMID 34356481, 2021).
glioblastoma (5 papers, 2022 to 2025). The most malignant astrocytic tumor (WHO grade IV). "In this study, CAR-T cells were engineered to secrete both IL-15 and CCL19, and their efficacy was evaluated in a human glioblastoma orthotopic xenograft model." (PMID 40177238, 2025). "Genes that show higher expression in astrocytoma compared to glioblastoma were CX3CL1, CSF1 (MCSF), CCL3 (MIP1α), CCL4 (MIP1β), TGFα, FLT3LG, CXCL5, CCL19 while KITLG (SCF) and NGF were equally expressed in the two tumor types." (PMID 35301393, 2022).
leukemia (5 papers, 2014 to 2023). A malignant (clonal) hematologic disorder, involving hematopoietic stem cells and characterized by the presence of primitive or atypical myeloid or lymphoid cells in the bone marrow and the blood. "Silencing of CCR7 in leukemia cells, or one of its ligands CCL19 in mice, specifically diminished infiltration of the CNS, but not other tissues, in both murine and xenotransplantation leukemia models." (PMID 28491865, 2017).
Lyme disease (5 papers, 2014 to 2025). Lyme disease (named after the towns in the USA where the disease was first identified) is a bacterial infection caused by Borrelia burgdorferi. "When we compared the levels of serum CXCL9/CXCL10 among the acute Lyme patients with high liver enzyme levels, there was a significant association of high CXCL9/CXCL10 and CCL19 levels with elevated liver enzymes in the acute phase of Lyme disease." (PMID 24740099, 2014). "One report showed that while serum CCL19 was elevated in most patients with acute Lyme disease, it was more likely to remain elevated at post-treatment follow-up visits among patients who developed PTLDS." (PMID 37760644, 2023). "CXCL9, CXCL10 and CCL19 are three prominent chemokines that were elevated in our cohort of acute Lyme disease patients." (PMID 24740099, 2014). "Prior analyses in longitudinal cohorts of Lyme disease patients followed from the time of acute infection have noted trends in CCL19, IL-23, and IFNα expression associated with the development of PTLD." (PMID 40703523, 2025). "Lyme disease has been associated with the proinflammatory cytokines Interleukin-6, Interleukin-8, Interleukin-12, Interleukin-18 and interferon-gamma; the chemokines CXCL12, CXCL13 and CCL19 and increased levels of proinflammatory lipoproteins." (PMID 30149626, 2018). "The coordinated elevation of CXCL9, CXCL10 and CCL19 in acute Lyme disease is consistent with an ongoing host immune response in the draining lymph nodes accompanied by the generation of Borrelia - reactive effector T cells and their migration into the site of infection." (PMID 24740099, 2014). "Studies have shown multiple elevated immune markers in both acute Lyme disease (IL-6, IL-8, IL-12, IL-18, IFN-γ, CXCL12, CXCL13) and PTLDS (IL-6, IL-23, IFN-α, CCL19)." (PMID 37760644, 2023).
non-small cell lung carcinoma (5 papers, 2022 to 2025). A group of at least three distinct histological types of lung cancer, including non-small cell squamous cell carcinoma, adenocarcinoma, and large cell carcinoma. "In non-small cell lung cancer, CCL19 and CXCL11 reduced the receptor activator of nuclear factor-κB ligand/osteoprotegerin ratio, an indicator of osteoclast stimulation." (PMID 38075694, 2023). "Notably, a study has identified that CCL19-expressing fibroblastic reticular cells (FRCs) generate interconnected T cell environments (TEs) in human non-small cell lung cancer, including tertiary lymphoid structures and T cell tracks." (PMID 40340806, 2025).
B-cell chronic lymphocytic leukemia (4 papers, 2010 to 2021). "CXCL13 and CCL19 together can inhibit the TNFα-mediated apoptosis of the CD23+ CD5+ B cell lineage, which is the commonest malignant cell type in acute and chronic lymphocytic leukemia." (PMID 30819249, 2019).
coronary artery disease (4 papers, 2012 to 2023). "CCL19/CCL21-CCR7 is closely correlated with high coronary artery disease risk and is considered a novel homeostatic chemokine system that promotes atherogenesis by modulating monocyte adhesion and migration." (PMID 37063958, 2023). "A few studies have noticed elevated plasma levels of CCL19 and CCL21 in ApoE-/- mice with AS lesions, human CAP, and patients with coronary artery disease." (PMID 36187128, 2022).
diabetes (4 papers, 2017 to 2024). "Higher insulin levels were associated with higher CCL19, sTNFR1, amylin, and C-peptide levels on linear regression among participants who did not report a history of diabetes and with a self-reported history of diabetes on logistic regression." (PMID 28753646, 2017). "We observed associations between self-reported diabetes and the chemokines previously reported in the literature, including CXCL10 and interleukin-8 (IL-8), as well as identified a number of novel associations such as: CCL19, CCL20, CCL21, CXCL6, and CXCL11." (PMID 28753646, 2017). "In addition, higher levels of the cytokine receptors, sIL-6R and sTNFR1, and the chemokines, CCL19, CCL20, CCL21, and CXCL11, were also associated with a history of self-reported diabetes at the <10% level." (PMID 28753646, 2017). "Our results showed that FTY720 diminished TLOs formation in kidneys and decreased TLO-related chemokine CXCL13 and CCL19 expression, which is consistent with previous animal research on TLOs in EAE and diabetes." (PMID 33391465, 2021).
encephalitis (4 papers, 2013 to 2023). An acute inflammatory process affecting the brain parenchyma. "Moreover, in FIRES Th1-associated cytokines and chemokines, as well as IL-6, CCL2, CCL19, and CXCL1, resulted elevated when compared to the levels observed in encephalitis, which involved a broader network of cytokines/chemokines." (PMID 38078329, 2023). "CCL19, CXCL8, CXCL9, and CXCL10 were significantly increased compared to CSF from control patients and compared to levels in serum in patients with encephalitis, meningitis, and Ramsay Hunt syndrome whereas CXCL11 was only increased in CSF in VZV meningitis patients." (PMID 30777092, 2019). "We demonstrate that CNS complications caused by VZV virus are associated with highly elevated CSF levels of the chemokines CCL19, CXCL8, CXCL9, CXCL10, and the matrix metalloproteinase MMP-2 in patients with different CNS manifestations such as encephalitis, meningitis, and Ramsay Hunt syndrome." (PMID 30777092, 2019). "Expression of CCL3, CCL5, CCL7 and CCL19 chemokines could play a crucial role in recruitment of IFN-γ-producing CD8+ T cells into the brain, and in facilitating migration of effector macrophages for prevention of Toxoplasma encephalitis during acute stage of encephalitis." (PMID 23374751, 2013). "The patients with MOG antibody positive associated demyelination showed predominant elevation of B cell related cytokine/chemokines (CXCL13, APRIL, BAFF and CCL19) compared to MOG antibody negative demyelination group as well as other encephalitis groups (CXCL13 and CCL19)." (PMID 27575749, 2016).
Granuloma (4 papers, 2013 to 2025). A compact, organized collection of mature mononuclear phagocytes, which may be but is not necessarily accompanied by accessory features such as necrosis. "CXCL9 and MCP-3 have been shown to increase in blood in TB patients, whereas CCL19 has primarily been associated with granuloma formation and maintenance in mouse models of TB." (PMID 36561889, 2022). "Similarly, CCL19 mRNA labeling in lymph nodes was present in the interfollicular cortex and paracortex outside of lymphoid follicles but was noticeably less abundant and less intense than that associated with granuloma associated follicle-like structures." (PMID 40468399, 2025). "Of interest, at this time point IRF-8−/− granulomas exhibited high levels of CCL19 in the outer layers." (PMID 23717393, 2013).
lymph node metastasis (4 papers, 2022 to 2024). "A recent study reported that the tumour‐derived CCL19 was associated with lymph node metastasis and suppresses the CD8 T cell function, which was similar with our results." (PMID 39392128, 2024). "Tumor samples and normal tissue from 27 patients were analyzed and showed elevated CCR7 and CCL19 for patients with lymph node metastasis." (PMID 35203305, 2022). "Similarly, the downregulation of CCR7 in the bone-seeking variants could also be explained by its role and that of its ligands (CCL19 and CCL21) in lymph node metastasis." (PMID 35158871, 2022).
mantle cell lymphoma (4 papers, 2010 to 2022). Mantle cell lymphoma is a rare form of malignant non-Hodgkin lymphoma affecting B lymphocytes in the lymph nodes in a region called the ``mantle zone''. "In addition, Macrophage Inflammatory Protein-3 beta (MIP-3β), also called CCL19 is essential for the migration and spreading of mantle cell lymphoma." (PMID 28424405, 2017).
multiple myeloma (4 papers, 2019 to 2024). "Moreover, our group have reported that BCMA or CD19 CAR-T cells expressing IL-7 and CCL19 may represent a promising therapy for relapsed/refractory multiple myeloma or B cell malignancies." (PMID 39776916, 2024). "Notch1 signaling has been shown to play a role in CCL19-driven homing of CLL cells and Notch1 signaling inhibition in multiple myeloma was described to prevent tumor cell migration." (PMID 31676012, 2019).
prostate carcinoma (4 papers, 2014 to 2023). A carcinoma that arises from epithelial cells of the prostate gland. "Cochrane’s Q test did not provide evidence of heterogeneity between CCL18 (p = 0.767), CCL19 (p = 0.093), CCL24 (p = 0.935), CXCL17 (p = 0.210) and prostate cancer." (PMID 38075694, 2023). "Peng first examined CCL19 and CCR7 expression in samples from prostate cancer and found that CCL19 and CCR7 were significantly overexpressed in all five prostate cancer cell lines he detected." (PMID 30430424, 2019). "We found that murine prostate cancer cell line RM-1-conditioned medium impaired chemotactic movement of marrow-derived DCs and splenic cDCs toward CC chemokine receptor-7 (CCR7) ligand CCL19 in vitro and migration to draining lymph gland in vivo." (PMID 29850633, 2018). "In addition, CCL19 and CCL21 migrated dendritic cells in prostate cancer to inhibit cancer progression." (PMID 38075694, 2023).
sarcoidosis (4 papers, 2015 to 2022). Sarcoidosis is a multisystemic disorder of unknown cause characterized by the formation of immune granulomas in involved organs. "Expression of chemokine (C–C motif) ligand 19 (CCL19), was markedly increased in sarcoidosis tissues, CCL19 is a critical regulator of the induction of T cell activation." (PMID 36388923, 2022). "Likewise, we also verified the over-expression of several other inflammation-associated genes including CCL19, CXCL13, and CYP27B1 in the lung of both TB and sarcoidosis patients." (PMID 33097805, 2020). "Among 20 similar signature genes shared by TB and sarcoidosis identified through RNA-Seq analysis, we further confirmed similar over-expression of MMP12, ADAMDEC1, CCL19, CXCL13, and CYP27B1 in TB and sarcoidosis lungs." (PMID 33097805, 2020). "Eight upregulated transcripts were common to sarcoidosis lung granulomas (CSF3, SERTAD1, MMP9, CCL19, BCL3, AREG, PTGS, F3)." (PMID 33276795, 2020).
Sepsis (4 papers, 2022 to 2025). Sepsis is defined as life-threatening organ dysfunction caused by a dysregulated host response to infection. "Among circulating inflammatory proteins, CCL19 not only increased the risk of sepsis (28-day mortality), but was also strongly associated with sepsis (28-day mortality in critical care units)." (PMID 39176264, 2024). "CCL19 (OR = 1.810, 95% CI = 1.018 ~ 3.219, P = 0.043) and C-C motif chemokine 28 levels (CCL28) (OR = 3.791, 95% CI = 1.215 ~ 11.825, P = 0.022) significantly increased risk of sepsis (28-day mortality in critical care units)." (PMID 39176264, 2024). "Studies have shown a significant increase in plasma CCL19 levels in patients with sepsis, which may be related to sepsis severity." (PMID 39176264, 2024). "Further, IMHA in dogs has a similar cytokine profile to sepsis, while SRMA is associated with a systemic inflammatory response and the overproduction of cytokines interleukin (IL)‐6, IL‐17, transforming growth factor (TGF)‐β, vascular endothelial growth factor (VEGF) and CC‐motif ligand 19 (CCL19)." (PMID 40485041, 2025). "According to the MR analysis, we found that C-C motif chemokine 19 (CCL19), C-C motif chemokine 28 (CCL28), TNF-related apoptosis-inducing ligand (TRAIL), and vascular endothelial growth factor A (VEGF-A) levels were associated with an increased risk of sepsis-related outcomes." (PMID 39176264, 2024). "Among the molecular variables, IL-1Ra, IL-17A, CCL19, CX3CL1 and TNF were significantly higher in septic patients compared to the infection non-sepsis group." (PMID 37691028, 2023). "Additionally, the plasma levels of IL-1Ra, IL-17A, CCL19, CX3CL1, and TNF were significantly higher in septic patients compared to the non-sepsis group." (PMID 37691028, 2023). "However, research on the relationship between CCL19 and CCL28 and sepsis is currently limited." (PMID 39176264, 2024).
systemic sclerosis (4 papers, 2014 to 2025). A chronic disorder, possibly autoimmune, marked by excessive production of collagen which results in hardening and thickening of body tissues. "Dysregulated CCL21 and CCL19, ligands of ACKR4, were also revealed in human PAH and CCL21 appears to be a potential biomarker for predicting the risk of PAH in systemic sclerosis." (PMID 37449198, 2023). "A recent study demonstrated that CCL19 was more strongly expressed in systemic sclerosis (SSc) skin and was correlated to vascular inflammation, providing further evidence for the role of CCL19 in perivascular inflammation and immune cell recruitment." (PMID 25260647, 2014). "However, mRNA levels of CCL19 and CCL21, the ligands of CCR7, were not significantly different in lungs of patients with idiopathic PAH as compared to controls, although CCL19 is thought to be a sensitive marker for perivascular inflammation in systemic sclerosis." (PMID 33105588, 2020).
AIDS (3 papers, 2010 to 2025). A syndrome resulting from the acquired deficiency of cellular immunity caused by the human immunodeficiency virus (HIV). "Higher serum levels of CCL19 have been associated with poor prognostics of AIDS patients." (PMID 25147954, 2014). "We found that CCL19 but not CCL21 mRNA was increased 8-fold in lymph nodes at 12 weeks post infection, but only in animals that progressed to AIDS." (PMID 21203477, 2010).
allergic asthma (3 papers, 2021 to 2023). A asthma with a basis in a pathological type I hypersensitivity reaction. "They observed an elevation of GAB1 level in peripheral blood mononuclear cells from asthmatic patients during acute exacerbation, and further experiments found that GAB1 can regulate DC migration in allergic asthma by affecting CCL19/CCR7 signaling." (PMID 38057792, 2023).
allergic disease (3 papers, 2022 to 2025). An immune response that occurs following re-exposure to an innocuous antigen, and that requires the presence of existing antibodies against that antigen. "In addition, we observed evidence of intercellular communication via genes implicated in type 2 immunity (CCL11, CCL13, CD5L, IL4, IL5, IL13, IL24) and allergy-linked inflammation (CCL19)." (PMID 35483355, 2022). "In allergic diseases, CCL19 facilitates Th2 differentiation and contributes to allergic airway inflammation." (PMID 39011048, 2024).
ankylosing spondylitis (3 papers, 2014 to 2026). An autoimmune chronic inflammatory disorder characterized by inflammation in the vertebral joints of the spine and sacroiliac joints. "Likewise, the expression levels of CCL19 are significantly elevated in both hip ligament tissue and serum of ankylosing spondylitis (AS) patients compared to normal controls, suggesting a role of CCL19 in AS pathogenesis." (PMID 31068931, 2019). "However, the role of CCL19/CCL21 in ankylosing spondylitis is rarely reported and demands a more comprehensive understanding." (PMID 25260647, 2014).